BRCA2 (BRCA2 DNA repair associated)
Diseases named in the same sentence as BRCA2 in open-access papers (continued):
Sharing a sentence is not in itself a finding about the gene and the disease.
cancer (continued). "Given that BRCA1 and BRCA2 participate in the repair of DNA double strand breaks, here we have investigated whether variations, Single Nucleotide Polymorphisms (SNPs), in genes participating in other DNA repair pathway may be associated with cancer risk in BRCA carriers." (PMID 24698998, 2014). "PGD has been used to identify cancer predispositions in 22 common inherited cancer syndromes including breast cancer (BRCA1 and BRCA2), Gorlin syndrome, tuberous sclerosis, familial colorectal cancer, and retinoblastoma." (PMID 26237394, 2014). "Amongst 80 cancer patients for whom FMR1 data were available, only 27 (33.8%) were BRCA-positive, 21 carriers of BRCA1 and 6 of BRCA2 mutations." (PMID 25036526, 2014). "We and others have shown that the genome‐wide DNA damage that follows homozygous inactivation of BRCA2 leads to checkpoint activation and cell cycle arrest, rather than the unrestrained cellular proliferation typical of cancer." (PMID 24268522, 2014). "Among the genes with rare variants in the most individuals are BRCA1, BRCA2, APC, MLL2, and MLL3, genes which are commonly mutated in cancers." (PMID 24728327, 2014). "PARP inhibition is preferentially cytotoxic to cancer cells with BRCA1 and BRCA2 mutations, but that effectiveness is reduced in cells with intact BRCA function." (PMID 24784564, 2014). "PARP inhibitors are currently being evaluated in clinical trials because of the synthetic lethality caused in cancers with genetic makeups that renders HR repair inactive, such as BRCA1 or BRCA2 mutations." (PMID 25074383, 2014). "Notably, the knowledge of founder BRCA1 or BRCA2 mutations may provide more precise estimates of the prior probability of carrying a mutation in either genes and of the likelihood of a mutation carrier developing cancer." (PMID 24516540, 2014). "Incidence of cancer for all BRCA2 carriers was 323 events per 23,796 person-years of follow-up (PYFY), i.e. 0.014 (95% confidence interval, CI 0.012 0.015)." (PMID 25274085, 2014). "Breast cancer growth rates vary considerably among cancer patients; they grow significantly faster in younger women, in recurrent cancers and in patients with BRCA1 and BRCA2 mutations." (PMID 25379013, 2014). "Several recent publications suggest that pharmacological targeting of BRCA1 and BRCA2 can sensitize BRCA-wildtype cancers to platinum-based chemotherapy and PARP inhibition." (PMID 24624361, 2014). "In humans, breast cancer-susceptibility 1 (BRCA1) and breast cancer-susceptibility 2 (BRCA2) genes have been found to be mutated in a large number of early-onset breast or ovarian cancers." (PMID 24004841, 2013). "Inhibitors of PARP were shown to be highly selective for cancer cells that harbor homologous recombination (HR) deficiencies, such as those harboring mutations in BRCA1 or BRCA2 genes." (PMID 24098868, 2013). "Inhibitors of PARP were originally developed for cancers with homologous recombination deficiencies, such as those harboring mutations in BRCA1 or BRCA2 genes." (PMID 24098868, 2013). "High frequencies of ALDH+ cells were found in the non-basal ductular levels in BRCA1 mutation carriers (p = 0.03), but in the basal ductular level in BRCA2 cancer patients (p = 0.02)." (PMID 24188377, 2013). "As a comparison, only five known cancer genes that are mutated in >10 cancer types (NF1, EP300, BRCA2, MLL, ARID1A) are longer than 4,450 bp." (PMID 23718799, 2013). "PARP-1 inhibitors have been shown to be effective in selectively inducing synthetic lethality in cancer cells, particularly in BRCA1- or BRCA2-deficient tumours." (PMID 23405229, 2013). "The rationale for this restriction is that many known cancer-associated genes, even those involved in very basic cellular mechanisms such as BRCA2, demonstrate cancer-type specificity." (PMID 24349080, 2013). "The new test will initially cover twenty-five genes associated with different types of cancer, including eight currently-proprietary ones BRCA1, BRCA2 and MYH." (PMID 23885284, 2013).
cancer (continued). "Other studies have shown selective killing by PARP inhibition of cells from diverse tumor types bearing mutations in ATM, MRE11A, BRCA2, or the EWS-FLI1 translocation, suggesting that PARP is a bona fide hub for genetic interactions with cancer genes." (PMID 23390603, 2013). "The most important predisposing factors are germline mutations in inherited cancer susceptibility genes, most notably BRCA1, BRCA2, RAD51C, RAD51D and the mismatch repair genes." (PMID 23522120, 2013). "PIK3CA mutations were significantly more frequent in cancers from BRCAX patients (17.2%, 5/29) than BRCA2 (0%, 0/25) carriers (P = 0.030)." (PMID 23971979, 2013). "There was substantial variation in number and pattern of indel, however, with more and larger indels observed in BRCA1 and BRCA2 mutant cancers." (PMID 22608084, 2012). "Many other cancer-related genes such as Brca1 and Brca2 also show a strong co-expression with the Bc055324 gene." (PMID 23039964, 2012). "BRCA-positive cases include cancer patients and their relatives carrying different BRCA1 or BRCA2 mutations." (PMID 22187037, 2012). "HR-defective cells, including BRCA2-defective cancer cells, exhibit profound sensitivity to inhibitors of poly(ADP-ribose) polymerase (PARP); hence, cancers harboring mutations in BRCA2 can be treated effectively with PARP inhibitors." (PMID 22325354, 2012). "Multiple cancer predisposition genes have already been identified in high-risk Utah pedigrees identified in the UPDB, including BRCA1, BRCA2, and p16/CDKN2A." (PMID 22471249, 2012). "These similarities in mutational signatures contrast strikingly with differences in histology and gene expression profiles between BRCA1 and BRCA2 mutant cancers." (PMID 22608084, 2012). "BRCA1 and BRCA2 cancers are particularly responsive to some DNA damaging agents and inhibitors of DNA repair, notably PARP inhibitors." (PMID 22608084, 2012). "Mutational patterns, which are probably more closely related to the underlying biological defect, therefore appear to report similarities in disease pathogenesis between BRCA1 and BRCA2 mutant cancers better than cellular phenotype." (PMID 22608084, 2012). "In patients diagnosed with cancer we found 4 novel deleterious mutations (c.2805_2808delAGAT and c.3124_3133delAGCAATATTA in BRCA1; c.2639_2640delTG and c.5114_5117delTAAA in BRCA2)." (PMID 22655046, 2012). "Nonetheless, Rad51 associates with chromatin during DNA replication in BRCA2-defective cells, and elevated expression of Rad51, which is often found in radioresistant cancer cells, bypasses the BRCA2 dependency of HR repair." (PMID 22325354, 2012). "Network 1 genes failed to separate the good and bad outcome groups, even though certain cell proliferation genes are known to be associated with these cancers, such as ASPM in GBM and BRCA1 and BRCA2 in OV." (PMID 22956898, 2012). "Such evidence suggests that genetic or other risk factors that cluster in families modify the cancer risks conferred by BRCA1 and BRCA2 mutations." (PMID 22053997, 2011). "So, it seems that haploinsufficiency for BRCA1 or BRCA2 in heterozygous women contributes to progressive telomere shortening at a somatic and germline level, affecting the age of cancer onset in successive generations." (PMID 21829373, 2011). "Evidences suggest that BRCA1 part of the "Role of BRCA1, BRCA2 and ATR in Cancer Susceptibility" pathway significantly enhances the ability of TNF-α or IFN-γ to activate transcription from the promoters of NF-κB target genes." (PMID 21226955, 2011). "Studies of Utah high-risk pedigrees identified in the UPDB have lead to the discovery of multiple cancer predisposition genes including BRCA1, BRCA2, p16, and HPC2/ELAC2." (PMID 21619629, 2011).
cancer (continued). "Although BRCA1- and BRCA2-related cancers demonstrate somewhat distinct picture of genetic abnormalities, they both have increased number of gross chromosomal aberrations and therefore higher tumor grade." (PMID 21819606, 2011). "Cancer risk has been shown to increase substantially with each decade of life for BRCA1- and BRCA2-mutation carriers." (PMID 22312502, 2011). "Inherited mutations also often produce a limited set or tissue type of cancer such as BRCA1 or BRCA2 with breast and ovarian tumors." (PMID 20111735, 2010). "We estimated risks of breast and other cancers for groups of relatives defined by the BRCA1 and/or BRCA2 mutation status of their index case." (PMID 20877337, 2010). "There are published reports of genetic modifiers of cancer risk in mutation carriers (for example, variants in AIB1 in BRCA1; variants in RAD51, FGFR2 and MAP3K1 in BRCA2; and variants in TNRC9 in BRCA1 and BRCA2)." (PMID 19843326, 2009). "More than 2,600 cancer predisposing mutations have been identified in BRCA1 and BRCA2 genes, on chromosome 17 and 13 respectively." (PMID 19825178, 2009). "Excluding those cases with normal BRCA1 and BRCA2 protein expression in the primary, 20 (80%) recurrent carcinomas had increases in either BRCA1 or BRCA2 protein while five (20%) did not have an increase in expression of either protein." (PMID 19602291, 2009). "In paired specimens, BRCA1 protein expression increased in 13/21 (62%) and BRCA2 protein expression increased in 15/21 (71%) of recurrent carcinomas with low or intermediate protein in the paired primary." (PMID 19602291, 2009). "The most effective, independent predictors of BRCA1 mutations were age at onset, HER2 status, and either ER or PR status, as compared with sporadic or non-BRCA1/BRCA2 cancers." (PMID 18275599, 2008). "In the context of high risk families studies have provided the evidence for at least two major cancer susceptibility genes: BRCA1 (17q21) and BRCA2 (13q12)." (PMID 18783588, 2008). "The cancer risks among BRCA1 and BRCA2 mutation carriers, and the polygenic variance, were assumed to be the same in the Ashkenazi and non-Ashkenazi versions." (PMID 18349832, 2008). "Pathway analysis confirming altered expression of cancer, cell proliferation and cell cycle pathways in BRCA1 and BRCA2 mutation carrier groups is consistent with the known functions of BRCA1 and BRCA2." (PMID 18497862, 2008). "In the following decade, as BRCA1 and BRCA2 testing became more common in patients with a personal or family history of cancer, numerous studies assessed cancer risks in carriers of these mutations." (PMID 17213823, 2007). "Various proteins that associate with centrosomes such as pericentrin, STK15/BTAK/Aurora-A kinase, ATR, BRCA1, BRCA2, have been shown to influence centrosome duplication in human cancer." (PMID 17081288, 2006). "For the BRCA2 group, the cost per additional cancer detected equates to £15 302 for CE MRI and mammography combined after excluding CE MRI for extended dominance." (PMID 17016484, 2006). "This is particularly true for the BRCA1 and BRCA2 groups, which suggested that the incremental cost per detected cancer with CE MRI (combined with mammography or with CE MRI alone) is £11 800 and £15 300 respectively when compared to mammography alone." (PMID 17016484, 2006). "For the BRCA1 (BRCA2) group, the number of cancers detected was three out of 13 (6 out of 12), 12 out of 13 (7 out of 12) and 12 out of 13 (11 out of 12) by mammography, CE MRI and CE MRI and mammography combined respectively." (PMID 17016484, 2006).
cancer (continued). "Nonetheless, the reason for the differences with our results are unclear, since we found that the BRCA2 protein was highly induced in a reproducible fashion in four different human cancer cell lines." (PMID 16434996, 2006). "Our results on BRCA2 cancers were quite similar to those of Palacios and colleagues and Lakhani and colleagues, although in the former study the BRCA2 cancers were more ER-positive and PgR-positive (on the basis of smaller sample set of 14 cases)." (PMID 15642173, 2005). "In the case of breast and/or ovarian cancer, the Cardiff laboratory conducts full mutation screening of all 22 relevant exons (45 fragments) of the BRCA1 gene and all 26 relevant exons (40 fragments) of the BRCA2 gene for a cancer-affected relative." (PMID 15583691, 2005). "Several previous studies have shown that DCIS is a characteristic feature of cancers in BRCA2 carriers." (PMID 16280055, 2005). "We screened the complete coding region of both genes in 451 individuals from 349 Belgian families referred to a family cancer clinic and identified 49 families with a BRCA1 and 26 families with a BRCA2 mutation." (PMID 15026808, 2004). "We performed mutation screening of the complete coding region of BRCA1 and BRCA2 in 349 unrelated Belgian families referred to our family cancer clinic and report here the nature and distribution of the mutations identified." (PMID 15026808, 2004). "Hypermethylation was observed in all of the histological stages of cancer examined and in patients of all ages except BRCA2 which is seen in only one patient with stage IC." (PMID 15574200, 2004). "RB1 co-deletion with BRCA2, due to synteny on chromosome 13q, may explain reduced efficacy of CDK4/6 inhibitors in BRCA2 mutant cancers." (PMID 41512445, 2026). "Although BRCA2 deficiency has been thought to drive mutations in cancer, these findings may suggest increased type I IFN in BRCA2-deficient cancer may stimulate NK cell killing of cancer cells." (PMID 41139700, 2026). "In this context, we leveraged BRCA2 and PARP as a synthetic lethal target pair to consolidate the use of small molecule inhibitors of RAD51-BRCA2 protein-protein interaction as inducers of the BRCAness phenotype that sensitizes BRCA2-functional cancer cells to PARP inhibitors." (PMID 41704388, 2026). "Another international, longitudinal cohort study enrolled 4,332 women with P/LP BRCA1 or BRCA2 variants but who had never had any cancer diagnosis." (PMID 41488281, 2026). "Subthemes arising under this theme were: general cancer risks and management options (7/19, 36.8%), cancer risks based on family history/ancestry (4/19, 21.1%), insurance (4/19, 21.1%), other genes beyond BRCA1/BRCA2/PALB2 (3/19, 15.8%) and variants of uncertain significance (1/19, 5.3%)." (PMID 40081871, 2025). "It was recently shown that a substantial percentage of BRCA1 and BRCA2 mutated cancers do not lose their wild type allele through locus-specific LOH43." (PMID 41034557, 2025). "According to the Cancer Risk Estimates Related to Susceptibility (CARRIERS) Consortium, 2021, the prevalence of pathogenic variants of BRCA among women with BC was estimated to be 1·3% (associated with BRCA2) and 0·8% (associated with BRCA1)." (PMID 40626014, 2025). "An observational cohort study for the diagnosis of various cancers in the UK Biobank (UKB, N = 453,541) were recruited at ages of 40–69 years Association of germline pathogenic variants (PVs) in BRCA2 and published cancer‐specific PGS with cancer risk was tested using Cox proportional hazards model." (PMID 40462315, 2025).
cancer (continued). "While most heterozygous carriers do not appear to have significantly increased cancer risks, susceptibility to cancer, including CRC, is well established for carriers of heterozygous pathogenic variants in FANCS/BRCA1, FANCD1/BRCA2, FANCN/PALB2, FANCJ/BRIP1, and FANCO/RAD51C." (PMID 41155398, 2025). "Furthermore, we found a significant interaction effect between BRCA2 and PGS on the risk of two cancers (female breast and prostate) where the PGS effect was weaker in carriers than in noncarriers." (PMID 40462315, 2025). "Biallelic loss of HRR genes, especially BRCA1, BRCA2, RAD51D, RAD51 C, and PPP2R2 A was linked to higher HRD scores in BRCA-associated cancers, while BARD1, RAD51D, RAD54L, BRCA1, and MRE11 were associated with elevated HRD scores in in other cancer types (non-BRCA cancers)." (PMID 40420266, 2025). "Although the BRCA2 variant did not contribute to the current phenotype, it has important implications for future cancer surveillance and family risk assessment." (PMID 41226549, 2025). "For eight cancers where cancer‐specific PGS is available, each PGS was significantly associated with its respective cancer risk and independent of BRCA2, HR > 1.25 for 1 unit increase in standard deviation, all ps < 0.001." (PMID 40462315, 2025). "Among them, 11 BRCA1 and BRCA2 PV carriers had a history of cancer." (PMID 39825003, 2025). "Pathogenic variants in BRCA2 can disrupt these interactions, impairing RAD51 filament assembly, compromising HR efficiency, and ultimately leading to genomic instability and increased cancer predisposition." (PMID 41283249, 2025). "The broader gene analysis was driven by the possibility of misclassified primary tumours and increasing evidence that genes associated with other cancers (e.g., BRCA1, BRCA2, CHEK2) may also influence CRC risk through shared pathways." (PMID 40627234, 2025). "In addition to these established cancer risks, a growing body of clinical data suggests BRCA1 and BRCA2 carriers also have an increased risk of GC." (PMID 41256354, 2025). "Similarly, CX5461 has been used for early-stage clinical studies of BRCA1-, BRCA2-, and PALB2-mutated cancers." (PMID 41203590, 2025). "Among these, the BRCA2 Met1915Thr (rs4987117) variant has drawn particular attention due to its location within the RAD51-binding BRC repeat domain—critical for DNA repair function—and its potential role in modulating cancer risk." (PMID 40843725, 2025). "BRCA1 and BRCA2 proteins are required for homology-directed repair (HDR) of DNA double-strand breaks (DSBs), and germline mutations in BRCA1 or BRCA2 genes predispose individuals to breast, ovarian, and other cancers." (PMID 40669753, 2025). "Certain mutations resulting from these error-prone repair processes may contribute to cancer onset or progression, which helps explain, at least in part, the elevated cancer risk associated with BRCA1 and BRCA2 mutations." (PMID 41373813, 2025). "Interestingly, Metascape for the first time demonstrated a physical interconnection between CALML3 and DNA repair proteins (BRCA2—Breast Cancer Gene 2, BLM—Bloom syndrome protein, SLX4—Structure-Specific Endonuclease Subunit)." (PMID 41465209, 2025). "Poly(ADP-ribose) polymerase (PARP) inhibitors (PARPi) induce cell death by exploiting the absence of homologous recombination in cancer cells harboring mutations in the BRCA1/BRCA2 genes." (PMID 41347092, 2025). "The elevated CBC/OC cancer risks, together with previous results, suggest that females found to carry BRCA1/BRCA2 PVs may wish to consider risk-reducing options such as contralateral mastectomy and risk-reducing bilateral salpingo-oophorectomy after BC." (PMID 39475295, 2025).